PGK1 (phosphoglycerate kinase 1)
Diseases named in the same sentence as PGK1 in open-access papers (continued):
Sharing a sentence is not in itself a finding about the gene and the disease.
hemophilia A (1 paper, 2021). The most common form of hemophilia characterized by spontaneous or prolonged hemorrhages due to factor VIII deficiency. "Patient 1 has sought our assistance with pregnancy planning in order to avoid the risk of giving birth to a male child affected with either hemophilia A or PGK1 deficiency." (PMID 34445777, 2021). "Patient 1 presents with severe hemophilia A due to being a carrier of a F8 mutation inherited from her father in addition to the PGK1 mutation inherited from her mother." (PMID 34445777, 2021).
Hyperglycemia (1 paper, 2025). An increased concentration of glucose in the blood. "Our multilevel investigation demonstrated that PGK1 induction in GDM placentas parallels antioxidant dysfunction, linking hyperglycemia to OS through Keap1-Nrf2 suppression." (PMID 40959277, 2025).
Hypoglycemia (1 paper, 2019). A decreased concentration of glucose in the blood. "We next investigated whether PGK1 and DJ1 proteins are localized to telomeres by chromatin immunoprecipitation and telomere QPCR in cells treated in the presence or absence of hypoglycemia and CRT0063465." (PMID 31401411, 2019).
Impaired glucose tolerance (1 paper, 2026). An abnormal resistance to glucose, i.e., a reduction in the ability to maintain glucose levels in the blood stream within normal limits following oral or intravenous administration of glucose. "Proteomic analysis revealed that individuals with impaired glucose tolerance (IGT) had reductions in proteins regulating glycolysis (PGK1, G3P), lipid metabolism (ACBP, ARF1), glucose transport (14-3-3B), and insulin secretion (STARD10, CAPDS) compared with normal glucose-tolerant (NGT) individuals." (PMID 41854718, 2026).
inflammatory bowel disease (1 paper, 2024). A spectrum of small and large bowel inflammatory diseases of unknown etiology. "Similarly, in inflammatory bowel disease, higher PGK1 expression levels were linked to disease severity, suggesting its potential as an inflammatory biomarker." (PMID 39712033, 2024).
insomnia (1 paper, 2020). A sleep disorder characterized by difficulty in falling asleep and/or remaining asleep. "The insomnia-associated gene of LDHA has co-expression links with predicted genes of PGK1 and RARS." (PMID 32830860, 2020).
Insulin resistance (1 paper, 2011). Increased resistance towards insulin, that is, diminished effectiveness of insulin in reducing blood glucose levels. "Finally, in metabolism we found concordant upregulation of oxidative stress-response genes such as Gfpt2 and glycolysis related genes such as Pgk1, with downregulation of gluconeogenesis gene Eno2, and diacylglycerol kinases Dgka and Dgkh, important in fatty acid metabolism and insulin resistance." (PMID 21696628, 2011).
intestinal cancer (1 paper, 2023). "Besides PGK1, which we described in the results part, another unfavorable prognostic gene MMP14 conferred chemoresistance in the APCMin-mouse model of intestinal cancer." (PMID 37654625, 2023).
intrahepatic cholestasis (1 paper, 2022). A cholestasis characterized by impairment of the bile flow caused by obstruction located in the liver. "Our results are consistent with those obtained by Wei & Hu 30, who detected a marked augmentation in some glycolytic genes including GLUT-1 and PGK1 in placentas of women with intrahepatic cholestasis due to a marked hypoxia." (PMID 34975312, 2022).
ischemia (1 paper, 2022). A hypoperfusion of the BLOOD through an organ or tissue caused by a PATHOLOGIC CONSTRICTION or obstruction of its BLOOD VESSELS, or an absence of BLOOD CIRCULATION. "Additionally, PEP-1-PGK1, but not Con-PGK1, mitigated ischemia-induced hyperlocomotion 1 d after ischemia and 4 d after ischemia of neuronic cell death." (PMID 36260875, 2022).
kidney chromophobe cell carcinoma (1 paper, 2022). "Indeed, PGK1 was specifically overexpressed in KIRC, but not in kidney chromophobe cell carcinoma (KICH) or kidney renal papillary cell carcinoma (KIRP) when PGK1 expression profiling was assessed across all kinds of tumor tissue samples from GEPIA database." (PMID 35121728, 2022).
laryngeal carcinoma (1 paper, 2025). Carcinoma that arises from the laryngeal epithelium. "PXN and PGK1 are considered as potential prognostic markers for HPV-positive laryngeal cancer." (PMID 40821990, 2025). "PXN and PGK1 are expected to be potential prognostic markers for HPV-positive laryngeal cancer." (PMID 40821990, 2025). "Key genes like CDC42, PXN, ITGB1, PGK1, SLC2A1, ISG15 and ICAM1, affected by HPV, display distinct functional alterations and complex correlations in laryngeal cancer progression." (PMID 40821990, 2025).
lentivirus infection (1 paper, 2022). Virus diseases caused by the Lentivirus genus. "However, reconstitution of Smyd3 by lentivirus infection in Smyd3-/- MEF cells recovered the induction of expression of Pgk1 and Vegf compared to the empty virus control (pHAGE)." (PMID 36273580, 2022).
lung injury (1 paper, 2025). "A study on acute lung injury revealed that PGK1 promotes M1 macrophage polarization by regulating NLRP3, thereby participating in the pathophysiology of acute lung injury." (PMID 40177399, 2025).
mastitis (1 paper, 2022). Inflammation of breast tissue during lactation or postpartum due to an obstructed duct or infection. "When mastitis developed (T1/C1), GPI, TPI1, GAPDH, PGK1, PGAM1, ENO1, and PKM in the glycolysis/gluconeogenesis pathway were upregulated, which promoted pyruvate synthesis with large amounts of ATP production." (PMID 36335251, 2022).
mastocytosis (1 paper, 2023). A clonal myeloproliferative neoplasm characterized by the proliferation and accumulation of neoplastic mast cells in one or multiple organs or organ systems. "We might assume that the presence of phosphoglycerate kinase 1 only in patient samples and its inclusion in the PPI networks associated with the epithelial differentiation pathway may be linked to an altered cell proliferation process and to the neoplastic feature of mastocytosis." (PMID 37834061, 2023).
mental disorder (1 paper, 2017). A disease that has its basis in the disruption of mental process. "In humans, Pgk1 is also important for tumor growth and DNA replication/repair and mutations in Pgk1 are associated with myopathy, mental disorders and hemolytic anemia." (PMID 29059239, 2017).
metastasis (1 paper, 2018). The spread or migration of cancer cells from one part of the body (where they first appeared) to another. "PGK1 overexpression was positively correlated with the tumor clinical stage (I vs. II–III; P < 0.001), pathological type (adenocarcinoma vs. others; P = 0.007), histological grade (G1 vs. G2 vs. G3; P = 0.002), and lymph node metastasis (negative vs. positive; P < 0.001)." (PMID 29416645, 2018).
metastatic cancer (1 paper, 2020). A carcinoma which has spread from the original site of growth to another anatomic site. "Given its relevance in several types of metastatic cancer, PGK1 was confirmed as a potential target by our proteomic experiments." (PMID 31945087, 2020).
mucinous carcinoma (1 paper, 2021). "In addition, GLUT1, HK2, PFKP, PGK1, and PKM2 had higher expression levels in mucinous carcinoma." (PMID 34277429, 2021).
Myalgia (1 paper, 2020). "Glyceraldehyde-3-phosphate dehydrogenase (GAPDH) is another glycolytic enzyme that was found significantly upregulated in TMD myalgia patients and, like PGK1, is overexpressed in various malignancies and correlates positively with tumor progression." (PMID 32272779, 2020). "In this context, it may be hypothesized that conditions of oxidative stress involved in myalgia may increase the need of PGK1 and GAPDH." (PMID 32272779, 2020). "Over-expression of salivary PGK1 in TMD myalgia patients has never been described so far; however, the involvement of the enzyme in TMD remains unclear and needs further evaluation." (PMID 32272779, 2020).
non-spherocytic hemolytic anemia (1 paper, 2012). "PGK1 deficiency is generally associated with moderate to severe non-spherocytic hemolytic anemia, often accompanied with central nervous system (CNS) disorders." (PMID 22348148, 2012).
osteoarthritis (1 paper, 2025). A noninflammatory degenerative joint disease occurring chiefly in older persons, characterized by degeneration of the articular cartilage, hypertrophy of bone at the margins and changes in the synovial membrane. "CBR‐470‐1, a specific inhibitor of PGK1, can reduce PGK1 activity to reverse the role of hypoxia in the progression of osteoarthritis." (PMID 39731281, 2025).
osteopetrosis (1 paper, 2021). Osteopetrosis, also known as marble bone disease, is a descriptive term that refers to a group of rare, heritable disorders of the skeleton characterized by increased bone density on radiographs. "At seven loci, there was a single putative causal gene: Abca12 at a locus for adult neurogenesis; Epha4 (stress-coping strategy); Pkn2, Slit3, and Pgk1-rs7 (at three different loci for sleep); H60c (home cage activity); and Adcy1 (osteopetrosis)." (PMID 34311762, 2021).
psoriasis (1 paper, 2023). An autoimmune condition characterized by red, well-delineated plaques with silvery scales that are usually on the extensor surfaces and scalp. "Consistently, RT‒qPCR results showed that K17 KO also downregulated the mRNA levels of the proliferation markers K17, K16, PCNA, Cyclin D1 and key enzymes (GLUT1, PFKM, LDHA, HK2, PKM2, ENO1 and PGK1) in the IMQ-induced psoriasis-like model." (PMID 37497003, 2023). "Moreover, Ki67 expression and the mRNA levels of proliferation markers K17, K16, PCNA, Cyclin D1 and key enzymes (GLUT1, PFKM, LDHA, HK2, PKM2, ENO1 and PGK1) were also decreased in epidermal KCs of the IMQ-induced psoriasis-like model with local application of BI-D1870." (PMID 37497003, 2023). "RT‒qPCR results showed that KCs from psoriasis patients expressed higher mRNA levels of glycolytic transporters (GLUT1) and glycolytic enzymes (PFKM, LDHA, HK2, PKM2, ENO1 and PGK1) than those from healthy skin." (PMID 37497003, 2023).
ptosis (1 paper, 2019). The drooping of the upper eyelid. "We identified a novel hemizygous missense variant associated with PGK1 deficiency, c.1114G > A (p.G372S) in a male adult patient presenting with exercise intolerance and several episodes of rhabdomyolysis, ptosis, muscle weakness and mild cognitive disability." (PMID 31658606, 2019).
pulmonary arterial hypertension (1 paper, 2023). Pulmonary arterial hypertension (PAH) is a group of diseases characterized by mean pulmonary artery pressure >20 mmHg and elevated pulmonary arterial resistance leading to right heart failure. "This approach was used in a paper from this year that shows significant upregulation of SOCS3, ITGAL, NFIC, NCOR2, and PGK1 mRNA (qRT-PCR) in peripheral blood mononuclear cells from pulmonary arterial hypertension (PAH) patients compared to healthy controls (p ≤ 0.05)." (PMID 37762023, 2023).
rheumatoid arthritis (1 paper, 2020). A chronic, systemic autoimmune disorder characterized by inflammation in the synovial membranes and articular surfaces. "High expression of PGK1 has also been described in synovial tissue and blood of patients with rheumatoid arthritis, suggesting the involvement of the enzyme in the inflammatory process and synovial hyperplasia." (PMID 32272779, 2020).
sarcoma (1 paper, 2020). A usually aggressive malignant neoplasm of the soft tissue or bone. "HK2, GLUT1, PGK1, ENO1 and PKM were found positive correlation with SLC25A37 in sarcoma patients." (PMID 32831652, 2020).
schizophrenia (1 paper, 2015). A major psychotic disorder characterized by abnormalities in the perception or expression of reality. "Besides, several glucose metabolic enzymes such as aldolase C, triosephosphate isomerase, glyceraldehydes-3-phosphate dehydrogenase, phosphoglycerate kinase 1, phosphoglycerate mutase were consistently elevated in both brain tissues and PBMCs of schizophrenia as described in previous studies." (PMID 26169624, 2015).
serous ovarian cancer (1 paper, 2021). "Further results showed high PGK1 expression in patients with serous ovarian cancer indicated a poor prognosis of PFS." (PMID 34277429, 2021).
squamous cell neoplasm (1 paper, 2022). A neoplasm that is composed of squamous epithelial cells. "PGK1 has been found to increase in epithelial cells in the situation of anoxia and cellular damage and it has even been related to squamous cell neoplasm." (PMID 35565595, 2022).
temporal lobe epilepsy (1 paper, 2024). A localization-related (focal) form of epilepsy characterized by recurrent seizures that arise from foci within the temporal lobe, most commonly from its mesial aspect. "Thus, Pgk1 and Ywhaz could be used for time course gene expression analysis of brain changes from the latent period to the chronic period in a rat lithium–pilocarpine temporal lobe epilepsy model." (PMID 38791067, 2024).
tongue cancer (1 paper, 2021). A malignant neoplasm affecting the tongue. "The results of log-rank test demonstrated that PGK1, CYP19A1, PFKM, and ZC3H12D were associated with the OS in tongue cancer patients." (PMID 33758601, 2021). "Previous studies have reported that the expression of LEPR 42, PFKM 43, 44, PGK1 45, 46, CYP19A1 47, 48, SLC20A1 49, and ZC3H12D 50 were associated with tumorigenesis and progression in various tumor types, which support the further identification and exploring in tongue cancer." (PMID 33758601, 2021). "PGK1, SLC20A1, LEPR, CYP19A1, ZC3H12D, and PFKM were found to be independent predictors in tongue cancer." (PMID 33758601, 2021).
tongue tumor (1 paper, 2021). "In our study, we did find the abnormally upregulation of LEPR, PFKM and PGK1 in tongue tumor patients and their upregulation are related to patients' poor overall survivals." (PMID 33758601, 2021).
Tourette syndrome (1 paper, 2023). A neurologic disorder caused by defective metabolism of the neurotransmitters in the brain. "Variants located in these regions were found to be damaging in Tourette’s syndrome (SLITRK1) and Phosphoglycerate kinase 1 deficiency (PGK1); however, these events are certainly rare and supporting evidence regarding their pathogenicity is hard to gather." (PMID 36084042, 2023).
uterine corpus endometrial carcinoma (1 paper, 2022). A endometrial carcinoma (disease) that involves the body of uterus. "Individuals with uterine corpus endometrial carcinoma with “mutation” as the major type had the greatest PGK1 alteration frequency (>5%)." (PMID 36358653, 2022).
tumor (287 papers, 1984 to 2026). "Then, in vivo and in vitro results demonstrated that tumor-associated macrophages (TAMs) function as critical mediators in PGK1-driven immunosuppression." (PMID 42183839, 2026). "Overexpression or aberrant activation of PGK1 is frequently associated with malignant tumor behavior." (PMID 40529105, 2025). "Previous studies reported that PGK1 expression is consistently associated with the aggressive characteristics of tumor cells, including their proliferation, migration, and invasive abilities." (PMID 40771921, 2025). "We clarified that in patients with ESCC, elevated PGK1 levels were linked to poor survival, tumour size, lymph node metastatic status, and TNM stage." (PMID 40534132, 2025). "Phosphoglycerate kinase 1 (PGK1) is the first ATP-generating enzyme in glycolysis, and its expression is linked to tumor progression." (PMID 39285476, 2024). "We also demonstrated that both TMEM52B‐P18 and TMEM52B‐P20 interact with PGK1, implying that the tumor growth‐promoting role of both isoforms depends largely on their association with PGK1." (PMID 38940427, 2024). "For instance, PGK1 is the upstream regulator of β-catenin, which is known to be a tumor-associated oncoprotein that affects tumor growth, invasion, metastasis, angiogenesis." (PMID 37449059, 2023). "Our studies also validate tumor tissue and serum PGK1 levels are associated with poor prognosis of KIRC patients." (PMID 35121728, 2022). "Acetylated PGK1 initiates autophagy event by phosphorylation of Beclin1 Ser30 residue, causing for growth and poor prognosis for tumor cells." (PMID 36077431, 2022). "PGK1 expression was lower in tumor specimens containing somatic mutations of CDH1 (mutation prevalence 14.1%)." (PMID 34291087, 2021). "Other reports also show that PGK1 expression is associated with tumor progression and prognosis of patients with gallbladder cancer." (PMID 34291087, 2021). "Interfering with PGK1 restored the tumor volume and weight caused by downregulation of LHX9 expression." (PMID 34536269, 2021). "Many studies reported that PGK1 is highly expressed in various cancers, and its aberrant expression is associated with the poor prognosis of tumor patients." (PMID 34852326, 2021). "Nuclear Factor of Activated T Cells 5 is highly expressed in PDAC patients and is associated with tumor progression by positively modulating PGK-1." (PMID 33256814, 2020). "Higher PGK1 expression was positively related to larger tumor size, higher risk of lymphatic and distant metastasis, more advanced tumor stage and higher overall death." (PMID 32070368, 2020). "In PDAC, SMAD4 loss mediates PGK1 upregulation, which enhances glycolysis and contributes to aggressive tumor behavior." (PMID 32429474, 2020). "Aberrant high expression of NFAT5 inhibits tumor proliferation and progression by dampening its Warburg effect, which is partly caused by transactivation of PGK1." (PMID 31827081, 2019). "Its role in promoting tumor proliferation is linked to PGK1’s ability to promote tumor angiogenesis, DNA replication and repair, and cancer metastasis." (PMID 30679932, 2019). "PGK1-positive expression in the primary tumor was statistically significantly associated with poorer overall survival than PGK1-negative expression (p = 0.003)." (PMID 24376734, 2013). "Extracellular secretion of PGK1 by tumor cells increases angiostatin activity, causing inhibition of angiogenesis." (PMID 19221597, 2009). "In addition, its ability to inhibit phosphoglycerate kinase 1 (PGK1) alters tumor metabolism, potentially increasing the susceptibility of cancer cells to chemotherapy or cell death." (PMID 41149747, 2025). "As a hallmark of cancer metabolism, the overexpression of PGK1 in PTC may not only reflect metabolic reprogramming but also influence tumor progression through various downstream signaling pathways." (PMID 40771921, 2025).